PIK3CA (phosphatidylinositol-4,5-bisphosphate 3-kinase catalytic subunit alpha)
Diseases named in the same sentence as PIK3CA in open-access papers (continued):
Sharing a sentence is not in itself a finding about the gene and the disease.
ovarian adenocarcinoma (2 papers, 2023 to 2025). An adenocarcinoma that arises from the ovary. "SKOV3 was derived from ascites of ovarian adenocarcinoma and contains mutant ARID1A and PIK3CA, and is frequently more closely associated with clear-cell tumors." (PMID 37621654, 2023). "Treatment with CUR alone significantly inhibited the growth of human ovarian adenocarcinoma SKOV-3/CDDP CDDP-resistant subline cells by inhibition the gene expression of the antioxidant enzymes (SOD1, SOD2, GPX1, CAT, and HO1), transcription factor NFE2L2 and signaling pathway (PIK3CA/AKT1/MTOR)." (PMID 39859517, 2025).
pancreatic NETs (2 papers, 2015 to 2024). "Mutations of genes of the mTOR pathway, such as PTEN, TSC2 and PIK3CA, have been detected in about 16% of sporadic pancreatic NETs." (PMID 39199391, 2024).
papilloma (2 papers, 2022 to 2025). A benign epithelial neoplasm that projects above the surrounding epithelial surface and consists of villous or arborescent outgrowths of fibrovascular stroma. "Recent genomic studies have revealed PIK3CA mutations in approximately 69% of papilloma cases, typically in the absence of significant copy number alterations." (PMID 41244906, 2025). "It was suggested that an intraductal papilloma without PIK3CA mutation could progress directly to papilloma with ADH/DCIS." (PMID 34734332, 2022).
periodontal disease (2 papers, 2020 to 2024). "An overexpression of CTNNB1, FOS, JUN, GRB2, PIK3CA, and PIK3R1 may affect the cell cycle, resulting in excessive cell proliferation, and malignant transformation, besides being related to periodontal disease development and progression." (PMID 39517401, 2024).
pharyngeal cancer (2 papers, 2014 to 2016). "In our analysis, TCGA tumors enriched for the 4-NQO TGS were less frequently mutated for PIK3CA; which goes in line with the fact that PIK3CA mutations are found in 6-11% HNSCC, mostly in HPV-positive and especially in pharyngeal cancers." (PMID 27027432, 2016).
pilocytic astrocytoma (2 papers, 2020 to 2021). Pilocytic astrocytoma is a rare subtype of low-grade glioma of the central nervous system characterized by a well circumscribed, often cystic, brain tumor with a discrete mural nodule and long, hair-like projections that extend from the neoplastic astrocytes. "In PA, we could detect a mutation of the PIK3CA gene in 50% of our patients, which are rarely reported in pilocytic astrocytomas outside the spinal cord." (PMID 34193285, 2021). "One pilocytic astrocytoma which was wildtype in PIK3CA harbored a FGFR1 N546K mutation." (PMID 34193285, 2021). "Interestingly, in our study PIK3CA mutation seems to be associated with longer OS, which may be caused by its association with pilocytic astrocytoma, which in turn had the most favorable overall outcome." (PMID 34193285, 2021). "Both of these tumors lacked the accompanying PIK3CA or PIK3R1 mutation that is characteristic of RGNT, and both had epigenetic profiles aligning with pilocytic astrocytoma rather than RGNT." (PMID 32859279, 2020). "Additionally, DNT and pilocytic astrocytoma are characterized by either kinase domain tandem duplication or hotspot missense mutations, occasionally with accompanying NF1 or PTPN11 mutation, but lacking the accompanying PIK3CA or PIK3R1 mutation that characterizes RGNT." (PMID 32859279, 2020).
pituitary adenoma (2 papers, 2014 to 2019). "PIK3CA mutations have been identified in pituitary adenomas, including lactotroph adenoma, corticotroph adenoma and NFPA." (PMID 31796052, 2019). "Akt is overexpressed in pituitary adenomas, particularly NFPAs and mutations and amplifications of the phosphoinositide 3-kinase PIK3CA gene have been found in pituitary adenomas suggesting a role for the PI3K/AKT in pituitary adenoma formation." (PMID 25136513, 2014).
pleomorphic liposarcoma (2 papers, 2012 to 2017). Pleomorphic liposarcoma (PLS), the rarest subtype of liposarcoma (LS), is an aggressive, fast growing tumor located usually in the deep soft tissues of the lower and upper extremities.
polyp (2 papers, 2017 to 2018). A usually exophytic mass attached to the underlying tissue by a broad base or a thin stalk.
proliferative glomerulonephritis (2 papers, 2024). A constellation of renal disorders characterized by an increase number of cells in the glomerulus; these disorders generally present with nephrotic syndrome, and generally progress to end stage renal failure over a matter of weeks to years, depending on the etiology. "PIK3CA gain-of-function mutation in podocytes causes progressive proliferative glomerulonephritis in mice." (PMID 38842935, 2024).
schizophrenia (2 papers, 2022 to 2023). A major psychotic disorder characterized by abnormalities in the perception or expression of reality. "PIK3CA also encodes the PI3Ks enzyme and its activity is decreased in patients with schizophrenia." (PMID 37383091, 2023).
serous cystadenoma (2 papers, 2019 to 2022). A serous neoplasm in which the cysts and papillae are lined by a single layer of cells without atypia, architectural complexity or invasion. "In this study, we successfully established a novel in vitro model of LGSOC from serous cystadenomas and developed carcinoma cell lines by introducing oncogenic KRAS and PIK3CA mutations." (PMID 35326657, 2022). "We aimed to identify genetic variations in KRAS, BRAF, PIK3CA, and ERBB2 in LGSC/SBT/serous cystadenomas (SCAs) in a Japanese population." (PMID 31892193, 2019).
Skin rash (2 papers, 2011 to 2023). A red eruption of the skin. "TTP and OS to the ≥2nd line cetuximab-containing treatment according to KRAS, BRAF, PIK3CA mutations status, PTEN protein expression, AREG and EREG mRNA expression and grade of skin rash in the whole patient′ population." (PMID 21283802, 2011).
small bowel adenocarcinoma (2 papers, 2022 to 2023). "PIK3CA amplification and mutations have been poorly described in small bowel adenocarcinoma, but there were insufficient data to explain their impact on the disease." (PMID 35208504, 2022).
small bowel carcinomas (2 papers, 2019 to 2021).
tubular carcinoma (2 papers, 2018 to 2024). "Mutations in the PIK3CA gene may drive tumor growth in rare hormone receptor-positive cancers like mucinous carcinoma and tubular carcinoma." (PMID 39685105, 2024). "Of the remaining tubular carcinomas, 3 fell in IntClust 7 (with 16q loss and MAP3K1 mutations), 4 fell in IntClust 8 (1q gain, 16q loss and PIK3CA and GATA3 mutations) and 6 belonged to IntClust 4 (few copy number alterations and activation of immune pathways)." (PMID 29532008, 2018).
acinar adenocarcinoma (1 paper, 2022). "While, gene mutations including PTEN, MST1R, and PIK3CA were noted during transdifferentiation from acinar adenocarcinoma to LCNEC." (PMID 36507119, 2022).
acute pharyngitis (1 paper, 2024). An acute and painful inflammatory process that affects the pharynx. "Our initial exploration revealed that TR treatment for acute pharyngitis engages targets such as PIK3CA, IL6, AKT1, TNF, PTGS2/COX-2, among others." (PMID 39568590, 2024).
adrenocortical carcinoma (1 paper, 2024). "PIK3CA pathogenic gene variants are also associated with various types of cancers such as endometrial, breast, ovarian, bladder, colorectal Wilms tumour, hepatoblastoma, adrenocortical carcinoma and others." (PMID 39872006, 2024).
aggressive (1 paper, 2012).
Alzheimer disease (1 paper, 2021). A progressive, neurodegenerative disease characterized by loss of function and death of nerve cells in several areas of the brain leading to loss of cognitive function such as memory and language. "Ten DEGs, including IGF1, VEGFC, RAPGEF3, PIK3CA, Akt3, ITGB3, ITGA11, SPP1, NOS1, and ATP6V0B, were selected from Rap1, oxidative phosphorylation, and Alzheimer’s disease signaling pathways." (PMID 34359260, 2021).
ampullary adenocarcinoma (1 paper, 2013). "Of note, both ampullary adenocarcinoma samples with mutations in PIK3CA in this cohort of patients occurred in the pancreaticobiliary-like subgroup." (PMID 23776447, 2013).
anaplastic ependymoma (1 paper, 2023). Anaplastic ependymoma is a rare, malignant type of ependymoma that most often arises in the supratentorial region of the brain of children and young adults and that manifests with variable symptoms including headaches, nausea, vision impairment, memory loss and difficulty walking. "The intronic variants found in the tumor of the present study were also detected in other tumors; for example, PIK3CA (rs3729674) was present in anaplastic ependymoma Grade III and ACP tumors." (PMID 37273678, 2023). "Results of a previous study reported intronic PIK3CA (rs3729674) and missense KDR (rs1870377) variants in anaplastic ependymoma Grade III." (PMID 37273678, 2023).
Arrhythmia (1 paper, 2026). Any cardiac rhythm other than the normal sinus rhythm. "In parallel, 902 arrhythmia-related genes were retrieved, yielding 24 overlapping targets, among which five hub genes (PIK3CA, CREBBP, NR3C1, SCN10A, and KCNA5) were identified." (PMID 42292832, 2026).
atrial tachycardia (1 paper, 2023). A disorder characterized by an electrocardiographic finding of an organized, regular atrial rhythm with atrial rate between 101 and 240 beats per minute. "Herein, we report the case of a 7-month-old girl with MCAP due to a PIK3CA somatic mosaic variant who presented with atrial tachycardia, finally diagnosed as pulmonary arterial hypertension (PAH)." (PMID 37614820, 2023).
autism spectrum disorder (1 paper, 2023). A spectrum of developmental disorders that includes autism, and Asperger syndrome. "Mutations in the genes in the PI3K-Akt-mTOR signaling pathway, comprising PIK3CA, PTEN, mTOR, and PPP2R5D have been reported in patients with autism spectrum disorder/development delay and macrocephaly." (PMID 36838876, 2023).
autoimmune disease (1 paper, 2024). A disorder resulting from loss of function or tissue destruction of an organ or multiple organs, arising from humoral or cellular immune responses of the individual to their own tissue constituents. "Notably, TBK1 and PIK3CA have been reported to play key roles in various autoimmune diseases and are potential therapeutic targets." (PMID 37823298, 2024).
Becker nevus (1 paper, 2025). "This suggests that patients with both Becker nevus and SOD may share a common genetic alteration involving ACTB, thereby supporting the potential value of investigating ACTB mutations in addition to PIK3CA mutations in such cases." (PMID 41356493, 2025).
Bladder Paraganglioma (1 paper, 2024). A benign or malignant extra-adrenal sympathetic paraganglioma arising from the urinary bladder. "A pathogenic somatic PIK3CA variant has only been reported once in the context of PPGLs, in a patient with bladder paraganglioma who also carried the H1047R mutation." (PMID 39684472, 2024).
brainstem glioma (1 paper, 2016). "A genomic profiling study of nine adult brainstem gliomas identified one BRAF V600E mutation and two PIK3CA mutations." (PMID 27556016, 2016). "Other mutations that have been reported in adult brainstem glioma, such as mutations in PDGFRA, PIK3CA, and PPM1D, are also potentially targetable with drugs that are either already commercially available or in development." (PMID 27556016, 2016).
breast NETs (1 paper, 2022). "PIK3CA is another of the most commonly mutated genes in IDCs, especially in the luminal A subtype, where most breast NETs also fit." (PMID 36085291, 2022). "Previously, PIK3CA pathogenetic or unknown variants have been reported in breast NETs in 7–20% of cases, in studies with smaller sample sizes and more limited sequencing." (PMID 36085291, 2022). "In our breast NET cohort, only 9% of tumours harboured PIK3CA pathogenetic or unknown variants, while the rate was 31% in the TCGA IDC material." (PMID 36085291, 2022).
breast SCC (1 paper, 2022). "Further studies regarding predictive and prognostic biomarkers in breast SCC (including PIK3CA and PD-1 expression) are needed." (PMID 35029184, 2022).
cardia cancer (1 paper, 2021). A malignant neoplasm involving the cardia of stomach. "According to our results, we recommend testing for PIK3CA amplification in intestinal-type cardia cancer patients, as they may benefit from targeted therapy." (PMID 34168977, 2021).
cecum cancer (1 paper, 2019). "The prevalence of PIK3CA variants increases continuously from rectal to cecum cancers, supporting the ‘colorectal continuum’ paradigm, and an important interplay of gut microbiota and host immune/inflammatory reaction." (PMID 31080553, 2019).
Cerebral ischemia (1 paper, 2022). Restriction of arterial blood supply to the brain associated with insufficient oxygenation to support the metabolic requirements of the tissue. "Accumulating evidence has confirmed that, under the injuries of stroke, cerebral ischemia, and I/R and activation of PI3K/Akt or PI3K/Akt/mTOR signaling pathway, PIK3CA, PIK3R1, AKT1, MAPK1, MAPK3 are main genes that play important roles in promoting cell survival and reducing cellular apoptosis." (PMID 35432563, 2022).
clear cell ovarian tumor (1 paper, 2021). "It was also observed that HDAC inhibition significantly suppressed the tumor growth in an ARID1A−/−/PIK3CAMUT genetic clear cell ovarian tumor mouse model and this similar molecular condition of ARID1A deletion and PIK3CA mutation is present in the IU-TAB-1 cell line." (PMID 34136086, 2021).
colitis (1 paper, 2025). Inflammation of the colon. "SCFA treatment led to a change in the expression of miR-10a-5p, which binds to the 3′UTR of pik3ca and inhibits PI3K-Akt pathway activation, leading to colitis alleviation." (PMID 40004537, 2025).
congenital heart disease (1 paper, 2019). A heart disease that is present at birth. "Among these genes, AKT1, PDPK1, CDC42, AKT3, and PIK3CA have concrete evidences shown in relation with congenital heart disease; even two of them (AKT1, CDC42) have explicit association with VSD." (PMID 31440271, 2019).
craniopharyngioma (1 paper, 2019). A benign, partly cystic, epithelial tumor of the sellar region, presumably derived from Rathke pouch epithelium. "Both the PIK3CA and the TSC2 mutations were observed in two patients in our study, suggesting that the roles of PIK3CA and TSC2 merit further investigation as to their contributions to the etiology of craniopharyngioma." (PMID 31712784, 2019).
developmental venous anomaly (1 paper, 2025). "We confirmed that 96% of cavernous malformations that are satellites of a developmental venous anomaly carried a PIK3CA variant and increased the relative haemorrhagic risk by 3 ± 0.31 (P = 3.8.10−3)." (PMID 41216139, 2025). "Finally, we confirmed that developmental venous anomaly is a radiological landmark of PIK3CA." (PMID 41216139, 2025).
Dravet syndrome (1 paper, 2025). "Two of the 15 patients with SEF and two of the 27 patients with DEE underwent other genetic testing, including direct sequencing for PIK3CA and commercial‐based panel sequencing for Dravet syndrome." (PMID 39915231, 2025).
eccrine carcinoma (1 paper, 2012). An adenocarcinoma with eccrine differentiation arising from the sweat glands.
embryonal tumors (1 paper, 2012). "Moreover, various reports have described activating mutations in the PIK3CA gene encoding the catalytic p110α isoform of PI3K in a variety of human cancers, including, breast, colon and ovarian cancer, as well as embryonal tumors." (PMID 23056595, 2012).
follicular adenoma (1 paper, 2023). "It has also been suggested that additional mutations are required, such as DICER, PIK3CA, and PTEN, for a follicular adenoma to be transformed to FTC." (PMID 37374164, 2023).
gallbladder tumors (1 paper, 2011). "Among these activating PIK3CA mutations were unique to gallbladder tumors." (PMID 21303542, 2011).
gastric diseases (1 paper, 2024). "It is hypothesized that the therapeutic efficacy of TYTW in counteracting gastric diseases stems from its ability to modulate key signaling pathways, thereby influencing PIK3CA activity and exerting anti-inflammatory effects." (PMID 38675376, 2024).
generalized lymphatic anomaly (1 paper, 2021). "PIK3CA mutations have also been implicated in some cases of diffuse capillary malformation with overgrowth (DCMO), lipomatosis of nerve (LON), and some complicated lymphatic anomalies (CLAs) including generalized lymphatic anomaly (GLA)." (PMID 34238334, 2021).
giardiasis (1 paper, 2024). An infection of the small intestine caused by the flagellated protozoan giardia lamblia. "Examining the mean expression of the four genes AKT1, CDKN2A, KRAS, and PIK3CA showed that three genes of AKT1, CDKN2A, and KRAS had increased expression in people with a history of giardiasis compared to healthy people." (PMID 38170269, 2024).
gingival tumor (1 paper, 2023). "In gingival tissue biopsy, we found that the mRNA expression level of KCNQ1, PIK3CA, and PIK3CB in the gingival tumor tissue of the proband was significantly increased." (PMID 37752101, 2023).
gliomatosis (1 paper, 2019). "A significant association between PIK3CA mutation and more disseminated disease at diagnosis, as defined by gliomatosis, multicentric lesions, or distant leptomeningeal lesions, was observed (46.2% vs. 11.1%, p = 0.004)." (PMID 31036078, 2019).
gliosarcoma (1 paper, 2019). A rare histological variant of glioblastoma (WHO grade IV) characterized by a biphasic tissue pattern with alternating areas displaying glial and mesenchymal differentiation (WHO). "We found frequent alterations in PIK3 genes in 3/10 gliosarcoma specimens, with the PIK3CA gene being mutated twice in one gliosarcoma and the PIK3R1 gene harboring indel-events in two samples." (PMID 30818875, 2019). "We found frequent alterations in PIK3 genes in 4/10 gliosarcoma specimens, with the PIK3CA gene being mutated twice in one sample and the PIK3R1 gene harboring the indel in two samples." (PMID 30818875, 2019).
glomerulopathy (1 paper, 2024). "To specifically investigate the role of PI3Kα in podocytes during collapsing glomerulopathy, we employed a genetic approach to remove PIK3CA specifically in these cells." (PMID 38842935, 2024).
Glucose intolerance (1 paper, 2023). Glucose intolerance (GI) can be defined as dysglycemia that comprises both prediabetes and diabetes. "Mice lacking adipose PIK3CA or the downstream kinase PDK1 exhibited glucose intolerance and liver steatosis." (PMID 37311757, 2023).